FGF21 (fibroblast growth factor 21)
Diseases named in the same sentence as FGF21 in open-access papers (continued):
Sharing a sentence is not in itself a finding about the gene and the disease.
Obesity (continued). "Therefore, FGF21 may be an effective therapeutic agent for the treatment of obesity and fatty liver disease." (PMID 37108717, 2023). "Thus, in mouse model of obesity induced by consumption of a sweet-fat diet, the catabolic effect of FGF21 was not sex-specific and hormonal, transcriptional and behavioral effects of FGF21 were sex-specific." (PMID 37469453, 2023). "Indeed, FGF21 is elevated in obesity, chronic kidney disease, metabolic syndrome, liver disease, and type 2 diabetes, and these pre-existing conditions may confound the findings." (PMID 36028609, 2023). "Therefore, we hypothesized that the synergistic function of GLP-1 and FGF21 could enhance the efficacy of diabetes and obesity treatments." (PMID 38116563, 2023). "In humans, an elevated FGF21 level in HF patients may be indicative of a FGF21-resistant state in response to chronic cardiac stress, as has been proposed in obesity, or a compensatory response to comorbid metabolic conditions, such as diabetes, which can precipitate HF." (PMID 36028609, 2023). "However, the overexpression of FGF-21 ameliorates obesity and liver steatosis." (PMID 37371624, 2023). "In addition, there are reports that BMP-9 could also enhance the expression of FGF21, thereby inhibiting obesity; FGF21 promotes the recruitment of beige adipocytes by upregulating the protein expression level of PGC1-α." (PMID 35886989, 2022). "Fibroblast growth factor 21 (FGF21) is a metabolic regulator produced mainly in the liver, which is induced in response to multiple stressors, including energy deprivation, amino acid deprivation, exercise, inflammation, and metabolic disorders, such as obesity." (PMID 36611740, 2022). "Thus, we hypothesized that melatonin suppresses the progression of obesity by increasing UCP1 expression dependent on FGF21." (PMID 36207302, 2022). "For example, FGF21 expression in liver tissues could be induced by fasting and a ketogenic diet, whereas overfeeding and obesity-inducing factors in the pancreas and white adipose tissue (WAT), by cold exposure in brown adipose tissue (BAT), and by exercises in skeletal muscle." (PMID 36618930, 2022). "Moreover, the relationship between serum FGF21 levels and BMI suggests that obesity-induced FGF21 resistance may occur in T1DM patients." (PMID 35192641, 2022). "Moreover, FGF21 can also limit inflammation in the pancreas of HFD-induced mouse models of obesity." (PMID 35909571, 2022). "However, the strong effect of both urinary lactulose and fecal MPO on FGF21 and FGF23, adipokines associated with increased intestinal permeability in mice and obesity in humans, suggests a complex interrelationship between these risk factors in the early pathogenesis of MetS." (PMID 36096405, 2022). "Administration of FGF21 to rodents or non-human primates causes considerable pharmacological benefits on a cluster of obesity-related metabolic complications including a reduction in fat mass and alleviation of hyperglycemia, insulin resistance, and dyslipidemia." (PMID 35448521, 2022). "In addition, aging, obesity, and insulin dosage are positive determinants of circulating FGF21." (PMID 35192641, 2022). "Importantly, global Pgam5-KO mice were found to be highly resistant to high-fat diet-related obesity, in association with reductions in serum triglycerides and lipid content in brown adipose tissue (BAT) and enhanced fibroblast growth factor 21 (FGF21) paracrine signaling." (PMID 39285950, 2022). "An increase of circulating FGF21 in MetS patients was hypothesized as a protective role against to metabolic stress or a compensatory upregulation to FGF21-resistance in tissues induced by obesity." (PMID 36474191, 2022). "Therefore, melatonin prevented obesity and insulin resistance dependent on FGF21 expression." (PMID 36207302, 2022).
Obesity (continued). "In contrast to elevated levels of endogenous FGF21 serum levels during obesity and obesity-related diseases, high endogenous FGF21 levels in mouse models with genetically modified mitochondrial function improve metabolism and mediate resistance to diet-induced obesity." (PMID 36034414, 2022). "Regarding Fgf21, this hepatokine was found to be almost always overexpressed in mice and humans with metabolic diseases, but such upregulation was previously demonstrated to result from the development of a resistant state to endogenous FGF21 action with obesity." (PMID 35409319, 2022). "We previously reported that fibroblast growth factor 21 (FGF21) is induced as an integrated stress response or ‘mitokine’ in autophagy-deficient liver tissue in an ATF4-dependent manner, leading to resistance to diet-induced obesity and insulin resistance through endocrine action." (PMID 35321438, 2022). "In addition, there is an association in the reduction of hepatic synthesis of FGF-21 in obesity, which fails to stimulate glucose uptake and reduces mitochondrial activity and thermogenesis." (PMID 36362238, 2022). "It is suggested that although FGF-19 and FGF-21 are activated under different conditions, they show a similar function in their controlling of glucose and insulin metabolism, energy and weight balance as well as lipid concentrations, particularly in metabolic disorders such as obesity or diabetes." (PMID 36362225, 2022). "Similarly, the negative association between circulating FGF21 and hippocampal and insular responses to sucrose ingestion was also stronger in healthy-weight individuals than in those with overweight or obesity." (PMID 35491674, 2022). "In particular, studies using mouse models revealed that exogenous administration of FGF21 induces a great number of metabolic effects in both, whole body and certain tissues, which are considered as beneficial with regard to prevention or treatment of obesity and T2DM." (PMID 34517929, 2021). "Furthermore, in vivo FGF21 gene delivery protected C57BL6/J mice against diet-induced obesity by decreasing adiposity and increasing uncoupling protein 1–dependent thermogenesis in brown fat and by boosting respiratory capacity in subcutaneous and perigonadal white fat." (PMID 34074713, 2021). "Given the liver-specific origin of circulating endogenous FGF21 and its ability to facilitate weight loss and reduced adiposity when used in various models of obesity, we envisioned utilizing this nonviral gene therapy strategy to deliver Hemagglutinin (HA)-tagged FGF21 to the liver in vivo." (PMID 34074713, 2021). "This evidence sparks the idea of whether FGF21 can be considered as a biomarker in obesity." (PMID 34578793, 2021). "Thus, upregulation of the miR-182-5p/FGF21/acetylcholine/PKA axis may be an effective approach to ameliorate obesity-induced metabolic diseases." (PMID 34264867, 2021). "The administration of recombinant FGF-21 in non-human models has been associated with an improved lipoprotein profile, increased glucose tolerance and insulin sensitivity, and reduced hepatic steatosis and obesity." (PMID 34822430, 2021). "FGF-21 could be the target of certain medications used to treat metabolic disorders and obesity." (PMID 34659937, 2021). "An increase of circulating FGF21 can be observed e.g., after acute exercising, long-term fasting, very low caloric diet, excessive intake of carbohydrates, in the postprandial period, after alcohol consumption, and lipid infusion, in type 2 diabetes (T2D), metabolic syndrome (MS) and obesity." (PMID 33805553, 2021). "However, the contributions of other tissues to FGF21 signaling and metabolic function could be important under particular metabolic conditions, such as cold exposure, obesity, or during exercise." (PMID 35046901, 2021). "It is hypothesised that proper action of FGF21 prevents the development of diet-induced obesity." (PMID 33670024, 2021).
Obesity (continued). "Thus, additional studies are required to tease apart the contribution of white Ad-FGF21 to circulating FGF21 levels that are characteristic of obesity, and whether Ad-FGF21 can impact other organs systemically, such as the brain." (PMID 35046901, 2021). "In diabetes and obesity treatment, FGF-21 may play a role in browning induction." (PMID 33669222, 2021). "However, our study contributes important data on the complex interaction between obesity and FGF21." (PMID 34762789, 2021). "However, it remains unknown if elevated FGF21 levels play a role in the effects of cardiac MED13 on obesity." (PMID 33390853, 2021). "A previous report illustrated that DNA demethylation of Fgf21 gene induced by peroxisome proliferator activate receptor α (PPARα) during the postnatal period could increase hepatic FGF21 expression, which may partly attenuate diet-induced obesity in adulthood." (PMID 34349728, 2021). "In addition to the complexity of FGF21 expression kinetics in response to different dietary or environmental stressors, FGF21 levels are paradoxically elevated in individuals with obesity, non-alcoholic steatohepatitis (NASH), and non-alcoholic fatty liver disease (NAFLD)." (PMID 35046901, 2021). "This suggests that the ability of FGF21 to correct melanocortin obesity may depend on sex." (PMID 34943946, 2021). "However, our data may indicate, that a link between FGF21 and preference for sweet taste exists in humans with severe obesity." (PMID 34836096, 2021). "Regarding the observed correlations, such as that between FGF21 concentration and mean velocity in the OF, these findings have no further consensus, as vertical activity and general mobility time were selected as the putative biomarkers for impaired obesity-related behavioural dysfunction." (PMID 34578793, 2021). "We aimed at investigating whether FGF21 affects metabolism inmale and female mice with the lethal yellow (Ay) mutation, which results in MC4R blockage and obesity development.Obese C57Bl-Ay male and female mice were administered subcutaneously for 10 days with vehicle or FGF21 (1 mg per1 kg)." (PMID 33659800, 2020). "FGF21 resistance in the CNS may play a critical role in obesity and metabolic syndrome." (PMID 32423100, 2020). "The pharmacological effect of FGF21 may depend on theanimal sex and etiology of obesity." (PMID 33659800, 2020). "Thus, female Ay-mice were resistantto anti-obesity effects of FGF21." (PMID 33659800, 2020). "Therefore, despite the beneficial effects of this factor on lipid metabolism and reducing angiogenesis, it is asserted that tissue resistance to FGF21 in obesity, fatty liver, and related metabolic disorders are responsible for an increased serum level of FGF21." (PMID 32095207, 2020). "Mice lacking FGF21 are more susceptible to the development of obesity-induced cardiac remodeling." (PMID 32610475, 2020). "Thus, insufficient expression of hepatic FGF21 and Sdf2l1 may lead to insulin resistance and hepatosteatosis in obesity and type 2 diabetes." (PMID 32978487, 2020). "Thus, FGF21 is presented as a promising agent for the treatment of obesity and insulin resistance." (PMID 32570721, 2020). "However, conditions such as obesity may lead to FGF21 resistance, and the level of KLB expression may modulate the response to FGF21." (PMID 31548436, 2019). "FGF21 may be a potential target in combating obesity-related skeletal muscle atrophy." (PMID 31312114, 2019). "This may suggest obesity-induced resistance to FGF21 due to the negative regulation by β-Klotho." (PMID 30927227, 2019). "FGF21 may be considered an independent marker of metabolic syndrome and obesity." (PMID 30927227, 2019). "We thus hypothesize that FGF21 may have a regulatory role in islet autophagy-mediated islet function and survival via AMPK-mTOR signaling, that is protective against glucolipotoxicity-induced islet dysfunction in obesity-associated T2DM." (PMID 31121855, 2019).
Obesity (continued). "In conclusion, weight loss in healthy overweight or obesity subjects did not affect FGF-21 levels." (PMID 31817052, 2019). "All these data point to the idea that FGF21 activation under glucolipotoxicity may induce autophagic flux via inhibition of AMPK-mTOR signaling in islets, and that FGF21 may be an important mediator of islet β-cell functions and pathophysiology related to obesity and T2DM." (PMID 31121855, 2019). "It has therefore been hypothesized that obesity leads to a FGF21-resistant state." (PMID 31548436, 2019). "Therefore, FGF21 is a therapeutic target for obesity and obesity-related metabolic diseases." (PMID 30041488, 2018). "This has led to speculations that obesity and related conditions could be FGF-21 resistant states." (PMID 30298107, 2018). "Moreover, FGF21 reduces physical activity and promotes torpor in Fgf21 transgenic mice: a favorable adaptive response to starvation, but an undesirable outcome in the context of obesity." (PMID 28677104, 2018). "Given the potential of FGF21 as a therapeutic target against metabolic disorders such as obesity and diabetes, these results could have promising clinical implications, being RT the most recommended training mode for the stimulation of FGF21." (PMID 30559681, 2018). "In conclusion, this study provides the first in vivo evidence that FGF21 expression is epigenetically regulated via DNA methylation and that the DNA methylation status, once established in early life, persists into adulthood, thereby contributing to the attenuation of diet-induced obesity." (PMID 29434210, 2018). "Thus, 39F7 might offer promising therapeutic potential for treating diabetes and obesity in the FGF21 signal pathway." (PMID 30068552, 2018). "Thus, preclinical evidence and clinical evidence corroborate that FGF21 may be an attractive candidate to combat obesity and TD2." (PMID 29987000, 2018). "The expression of FGF21 is induced by peroxisome proliferator-activated receptors (PPARs)-α and -γ in various stresses, such as starvation, ketogenic diet, amino acid deprivation, high-fat diet (HFD) or obesity, low-carbohydrate levels, autophagy deficiency, and mitochondrial stress (26, –28)." (PMID 29295856, 2018). "Therefore, FGF21 has been considered as potential therapeutic agent for obesity and T2DM45." (PMID 29311680, 2018). "While impaired FGF21-stimulated ERK1/2 phosphorylation in white adipose tissue has been proposed as evidence of FGF21 resistance during obesity, this impairment in FGF21 signaling could actually function as a beneficial physiological adaptation for excess nutrient disposal." (PMID 28580290, 2017). "Thus, our results demonstrate that Sp1 positively regulates the basal transcription of FGF21 in the liver and adipose tissue and contributes to the obesity-induced FGF21 upregulation in mouse adipose tissue and hepatic FGF21 upregulation in hepatocarcinogenesis." (PMID 28466020, 2017). "Recent findings suggest that the FGF21 is increased in four main circumstances: 1) mitochondrial diseases; 2) oxidative stress; 3) physically stressful situations, such as ketogenic diets and lactation; and 4) pathological physically stressful situations, such as obesity and critical illness." (PMID 28582462, 2017). "However, as FGF21 levels are elevated in obese and diabetic conditions we aimed to test if exogenous FGF21 is sufficient to prevent diabetes and beta cell loss in New Zealand obese (NZO) mice, a model for polygenetic obesity and type 2 diabetes." (PMID 28770320, 2017). "Thus, the inhibition of miR-34a by reducing Crtc2 activity in the liver could be beneficial in combating obesity and insulin resistance by promoting whole-body energy metabolism in an Fgf21-dependent manner." (PMID 29192248, 2017). "However, the mechanism of metformin and its effect on FGF21 in obesity is yet to be reported." (PMID 27057099, 2016).
Obesity (continued). "On the other hand, several studies including ours have demonstrated that hepatic FGF21 mRNA and serum FGF21 protein levels are increased in mice and humans with obesity and NAFLD38, 39, 40, suggesting that TG accumulation may trigger FGF21 expression in the liver." (PMID 27301791, 2016). "Moreover, long-term drinking of H2-water (water infused with H2) enhanced energy expenditure to improve obesity and diabetes in db/db mice accompanied by the increased expression of fibroblast growth factor 21 (FGF21) by an unknown mechanism." (PMID 28721265, 2016). "Thus, obesity has been proposed as an FGF21-resistance state." (PMID 26379627, 2015). "FGF21 transgenic animals show lower levels of serum insulin, glucose, triglycerides (TG), cholesterol, lower hepatic TG content, improved insulin sensitivity, resistance to diet-induced obesity, and a significantly extended lifespan compared with their wild-type counterparts." (PMID 26594197, 2015). "FGF21 may act as a compensatory signal to mitigate metabolic stresses due to obesity." (PMID 26379757, 2015). "And FGF21 may be a promising therapeutic target in obesity-related diseases." (PMID 25850006, 2015). "Bidirectional FGF21 and β-Klotho responses to exercise and caloric restriction (that is, decreased FGF21 and increased β–Klotho) have been reported; these responses were thought to mediate protection from obesity and obesity-induced nonalcoholic fatty liver disease in rats." (PMID 24603718, 2014). "Indeed, FGF21 has dramatic effects to reverse obesity in high-fat diet-induced obese mice." (PMID 24935677, 2014). "However, the sustained availability of nutrients and insulin that is seen in obesity may be facilitating FGF-21 expression." (PMID 24465939, 2014). "Thus, evaluation of FGF21 levels in children with obesity and glucose intolerance may shed further light on the possible regulatory actions of FGF21." (PMID 24883065, 2014). "Our previous studies suggest that this is through a mechanism by which hepatic FGF21 targets extra-hepatic adipocytes and adipose tissues via an endocrine mechanism for compensatory metabolic regulation and alleviation of metabolic diseases including fatty liver, obesity and diabetes." (PMID 23590285, 2013). "Furthermore, FGF21 has been reported to alleviate obesity in mice." (PMID 23755203, 2013). "However, as FGF21 is already increased in animal models of obesity and type 2 diabetes it is unknown how treatment with metformin will affect hepatic FGF21 expression and FGF21 plasma level and a careful evaluation of the time course is needed." (PMID 23118742, 2012). "Thus, it seems likely that there is a state of FGF-21 resistance in obesity or diabetes." (PMID 23152772, 2012). "Taken together, these findings demonstrate an important role of FGF21 as a hepatic hormone in the regulation of lipid metabolism and also suggest that FGF21exhibits the therapeutic characteristic necessary for an effective treatment of obesity and fatty liver disease." (PMID 21525989, 2011). "In addition, Fgf21 transgenic mice were resistant to diet-induced obesity." (PMID 21331285, 2011). "Furthermore, FGF-21 resistance might be found in obesity and in renal failure, leading to compensatory upregulation of this adipokine." (PMID 21206918, 2010). "In middle‐aged male mice with high‐fat diet‐induced obesity, 4 months of DPR attenuated cardiac hypertrophy and normalized heart failure markers, independently of FGF21 signaling." (PMID 41549510, 2026). "In our present study, another interesting sex-dependent effect of obesity and human HSPB1 overexpression was observed for Fgf21, a peptide hormone involved in energy homeostasis regulation." (PMID 40855499, 2025). "These plasma cytokine data support a generally heightened basal inflammatory state in obesity coupled with altered GDF-15 and FGF-21 responses to 48 h fasting." (PMID 40662191, 2025).